INS (insulin)
Diseases named in the same sentence as INS in open-access papers (continued):
Sharing a sentence is not in itself a finding about the gene and the disease.
fertility disorders (2 papers, 2012 to 2019). "Future studies would benefit from an intervention model for instance using the Ins2Akita+/− mouse on a controlled insulin regime, to prove the interrelation between the activation of the polyol and PKC pathway and the observed fertility disorders." (PMID 31506549, 2019).
focal segmental glomerulosclerosis (2 papers, 2018 to 2020). A renal disorder characterized by sclerotic lesions in the glomeruli. "The PPAR-γ agonist rosiglitazone, an antidiabetic drug in the thiazolidinedione class that increases insulin sensitivity in adipocytes, was well tolerated in children with drug-resistant focal segmental glomerulosclerosis (FSGS) in the FONT phase 1 trial." (PMID 29503620, 2018).
folate deficiency (2 papers, 2013 to 2023). A nutritional condition produced by a deficiency of FOLIC ACID in the diet. "Folate deficiency has also been reported to severely impede insulin biosynthesis and secretion from pancreatic β-cells." (PMID 37038237, 2023).
Gallbladder disease (2 papers, 2017 to 2023). "In addition, intake of meat rich in saturated fatty acids decreased insulin sensitivity and caused gallbladder disease and gallbladder dysmotility." (PMID 29169372, 2017).
glucocorticoid resistance (2 papers, 2023 to 2024). "The present study showed that the highest expression of adropin mRNA was found in the chronic stress group, and it was noticed that RQ was shifted to carbohydrate utilization in the CUMS compared to the AS group, despite insulin and glucocorticoid resistance." (PMID 36830976, 2023). "The toxic effect of ambient air pollution may lead to insulin and glucocorticoid resistance by interfering with the signaling pathways involved in inflammation." (PMID 38352708, 2024).
gram-negative bacterial infections (2 papers, 2023 to 2024). Infections caused by bacteria that show up as pink (negative) when treated by the gram-staining method. "Chico gene of Drosophila is a homologue of vertebrate IRS1-4, the functional loss of which reduced insulin signaling in D. melanogaster but increased the resistance to gram-positive and gram-negative bacterial infections." (PMID 38958928, 2024).
head and neck cancer (2 papers, 2011 to 2024). A primary or metastatic malignant neoplasm affecting the head and neck. "Malignant cells, and especially those originating from head and neck cancers, have a high glucose uptake, so an upregulation of glucose transporters is in accordance with a high sensitivity to insulin that is not blocked by miR-375." (PMID 21326242, 2011).
hepatocellular adenoma (2 papers, 2021 to 2025). A benign epithelial neoplasm arising from the hepatocytes. "Due to the insulin-mimetic effects, CCF developed already after a few days and progressed to hepatocellular adenomas and carcinomas." (PMID 34685767, 2021).
hippocampal atrophy (2 papers, 2025). "In addition, insulin prevents hippocampal atrophy neuronal loss, increasing neuronal density, doublecortin, PSD95 and BDNF levels." (PMID 41146261, 2025).
hyperalphalipoproteinemia (2 papers, 2013 to 2015). An autosomal dominant genetic condition caused by mutation(s) in the CETP gene, encoding cholesteryl ester transfer protein. "For instance, it was found that in healthy hyperalphalipoproteinemia subjects, several parameters that control the metabolism of plasma cholesterol and lipoproteins are related to a higher degree of insulin sensitivity." (PMID 26068179, 2015). "Our present and previous findings indicate that, in hyperalphalipoproteinemia, variations in several parameters that control the plasma lipoprotein metabolism are related to an increased degree of insulin sensitivity." (PMID 24267726, 2013). "In hyperalphalipoproteinemia cases, we found a diminished TG/HDL-C plasma ratio that has been deemed as critically dependent on insulin activity." (PMID 24267726, 2013).
hyperemesis gravidarum (2 papers, 2023 to 2024). Severe, intractable vomiting during pregnancy (usually the first trimester) accompanied by dehydration, weight loss, and electrolyte imbalances. "The increased abundance of lipid in early pregnancy may be a result of insufficient dietary energy intake (hyperemesis gravidarum), insufficient insulin dosing (lipolysis) or in response to specific dietary patterns (low-carbohydrate diet promoting lipogenesis; direct influence of a high-fat diet)." (PMID 37615689, 2023).
Hypergonadotropic hypogonadism (2 papers, 2012 to 2023). Reduced function of the gonads (testes in males or ovaries in females) associated with excess pituitary gonadotropin secretion and resulting in delayed sexual development and growth delay. "In detail, serum metabolomics highlighted different metabolic pathways involved in male hypogonadism and TRT, both in the case of insulin-sensitive patients with primary hypogonadism and in the case of IR patients with functional hypogonadism." (PMID 37334300, 2023).
Hyperoxaluria (2 papers, 2022 to 2023). Increased excretion of oxalates in the urine. "Third, vinegar have been suggested ameliorating the hyperoxaluria-induced renal injury by improving the gut microbiota, insulin sensibibity and metabolomic profiles." (PMID 37408009, 2023). "To test whether differences in insulin sensitivity can account for hyperoxaluria in ob/ob mice, we used two approaches." (PMID 35851836, 2022).
Hyperphenylalaninemia (2 papers, 2023). "Their conclusion was as follows: “After an acute high load of Phe in the PKU patients exists an absence of an increased secretion of insulin which suggests that a chronic hyperphenylalaninemia attenuates the insulin response”." (PMID 37367836, 2023). "Homocysteine levels were more remarkable among the overweight patients, with higher insulin, Peptide C, and HOMA-IR and lower QUICK index, and higher among patients with PKU vs. hyperphenylalaninemia and vs. controls, with homocysteine levels correlated with BMI, WC, and age." (PMID 38140392, 2023).
hyperplasia (2 papers, 2021 to 2022). An abnormal increase in the number of cells in an organ or a tissue with consequent enlargement. "Hyperplasia of the pancreas leads to an increased amount of insulin, corresponding to high plasma glucose levels." (PMID 35666987, 2022).
hyperprolinemia (2 papers, 2023 to 2025). Hyperprolinemia is when there isan excess of a particular protein building block (amino acid), called proline, in the blood. "Elevated levels of prolines and hydroxyprolines (hyperprolinemia) could cause derangement in systemic glucose metabolism via amino acid toxicity, leading to insulin dysregulation from impaired beta‐cell function." (PMID 40985218, 2025). "Moreover, hyperprolinemia is linked to impaired insulin secretion and dysregulated glucose homeostasis." (PMID 36923214, 2023).
Hypothermia (2 papers, 2017 to 2024). Reduced body temperature due to failed thermoregulation. "Hypothermia reduces insulin secretion and increases insulin resistance in animal models and in cardiopulmonary bypass patients." (PMID 29075530, 2017).
imbalance (2 papers, 2016 to 2022). "Prolonged period of fasting may have an adverse consequences for the patient such as headache, thirst, hunger, dehydration, electrolyte imbalance, distress, confusion, hypoglycemia, postoperative nausea and vomiting (PONV), and increased insulin resistance." (PMID 27222691, 2016).
invasive breast carcinoma (2 papers, 2018 to 2020). A carcinoma that infiltrates the breast parenchyma. "In this large prospective study, circulating IGF1 was inversely and independently associated with all-cause mortality in invasive breast cancer patients, and this association was consistent among patients with different strata of insulin and clinical characteristics." (PMID 32974138, 2020). "Immunohistochemical staining revealed that invasive breast cancer also shows increased phospho-insulin/IGF-1 receptor levels in tumor cells surrounded by CD163+ macrophages." (PMID 29367764, 2018). "Analysis of a TMA containing 90 samples from patients with invasive breast cancer showed that 78 of 90 (~ 87%) of these patients have Insulin/IGF1 receptors activated (upper pie diagram)." (PMID 29367764, 2018). "Our findings provide the rationale for further developing the combination of paclitaxel with IGF blockers for the treatment of invasive breast cancer, and Insulin/IGF1R activation and IGF+ stroma cells as potential biomarker candidates for further evaluation." (PMID 29367764, 2018). "In patients with invasive breast cancer, activation of Insulin/IGF-1 receptors increased to 87%." (PMID 29367764, 2018). "As insulin/IGF-1 receptors activation positively correlates with advanced tumor stage, we further analyzed biopsies from patients with invasive breast cancer." (PMID 29367764, 2018).
Iron metabolism disorders (2 papers, 2023 to 2024). "Iron metabolism disorders result in insufficient insulin secretion and IR; however, the relationship between iron metabolism and T2DM and its complications was unclear until the discovery of ferroptosis." (PMID 36882414, 2023).
islet cell carcinoma (2 papers, 2014 to 2024). "Six of seven pancreatic NEC-like G3NETs corresponded to the PanNET subtypes A1 or A2 (characterized by predominantly glucagon expression) and one to subtype B (characterized by insulin expression)." (PMID 39382626, 2024). "The first of these, published in 1981, was a report of a patient who developed tender subcutaneous nodules and was later diagnosed with insulin-secreting islet cell carcinoma, which may have contributed to her fat necrosis." (PMID 25298886, 2014).
Left atrial enlargement (2 papers, 2010 to 2018). Increase in size of the left atrium. "In obese patients, left atrial enlargement and electrical instability may be caused by elevated plasma volume, ventricular diastolic dysfunction, insulin resistance and enhanced neurohormonal activity." (PMID 20084192, 2010).
Left ventricular diastolic dysfunction (2 papers, 2021 to 2025). Abnormal function of the left ventricule during left ventricular relaxation and filling. "Older age, insulin therapy, and Chinese ethnicity were risk factors for left ventricular diastolic dysfunction in T2DM." (PMID 34646868, 2021). "Older T2DM patients of Chinese ethnicity and on insulin are about two times more likely to develop left ventricular diastolic dysfunction." (PMID 34646868, 2021).
leukocytosis (2 papers, 2017 to 2022). "ArtAB-DT104 and ArtAB-SW, but not ArtAB-Sb, stimulated insulin secretion in mice; however, unlike Ptx, ArtABs did not induce leukocytosis." (PMID 28572615, 2017).
lip sarcoma (2 papers, 2020). "Adipogenesis can be induced in well-differentiated liposarcoma (WDLPS) and dedifferentiated liposarcoma (DDLPS) cells by dexamethasone, indomethacin, insulin, and 3-isobutyl-1-methyl xanthine (IBMX)." (PMID 32849880, 2020).
macrocytic anemia (2 papers, 2024 to 2025). Anemia that is characterized by increased red blood cell volume. "KvLQT1-KO mice are also known to exhibit macrocytic anemia, intestinal absorption defects and enhanced insulin sensitivity." (PMID 38444763, 2024).
malignant brain tumors (2 papers, 2019 to 2023). "In summary, in this pilot study, we have provided data that suggest survivors of malignant brain tumours have an adverse cardiovascular risk profile characterized by a combination of excess total body and truncal fat mass, elevated total and LDL-cholesterol, and insulin resistance." (PMID 37253232, 2023).
medulloblastoma (2 papers, 2012 to 2016). A malignant, invasive embryonal neoplasm arising from the cerebellum. "The medulloblastomas are marked by a robust accumulation of many key glycolytic enzymes, including hexokinase II (HKII), pyruvate kinase M2 (PKM2), and glucose transporter type 4 (Glut4), which control glucose transport, especially into muscle and adipocytes in response to insulin stimulation." (PMID 22407012, 2012).
menopause (2 papers, 2020 to 2022). Cessation of menstruation, occurring in (e.g.) the human female usually around the age of 50. "Menopause is associated with reduced insulin sensitivity and a redistribution of visceral adipose tissue in favor of upper body and abdominal adiposity both of which are associated with reduced white and grey matter integrity." (PMID 35180116, 2022). "When menopause occurs as a result of hysterectomy, then the hormones estrogens and progesterone affect how the body cells respond to insulin." (PMID 32967655, 2020).
mesothelioma (2 papers, 2011 to 2021). A usually malignant and aggressive neoplasm of the mesothelium which is often associated with exposure to asbestos. "Most mesothelioma cells respond to insulin/IGF-I by increasing protein synthesis, as measured by methionine incorporation." (PMID 22216185, 2011).
metastasis (2 papers, 2020 to 2023). The spread or migration of cancer cells from one part of the body (where they first appeared) to another. "However, the blood glucose level of patient MI2 with synchronous liver metastasis was still lower than standard range, which immediately increased and maintained within standard range after treatment of liver metastasis, implying the insulin secretion capability of liver metastasis." (PMID 37251916, 2023). "Interestingly, in patient 2, both the primary and the corresponding liver metastasis only had few PDX1-positive cells (potential insulin producing cells), so perhaps the solitary liver metastasis (3 cm) did not grow to a size in which a low percentage of cells could have caused symptoms." (PMID 32103422, 2020).
myasthenia gravis (2 papers, 2005 to 2023). Myasthenia gravis (MG) is a rare, clinically heterogeneous, autoimmune disorder of the neuromuscular junction characterized by fatigable weakness of voluntary muscles. "One patient restarted insulin after rejection and failure of a pancreatic transplant for T1DM following development of IRAE-mediated grade 4 myasthenia gravis with myositis." (PMID 38027216, 2023).
Mydriasis (2 papers, 2018 to 2025). Abnormal dilatation of the iris. "Adrenaline is an important hormone in the response to stress because it increases glucagon concentration, which stimulates an increase in glucose and blocks insulin production thereby increasing heart rate, decreasing gastrointestinal motility, causing mydriasis, and increasing muscle energy." (PMID 30425790, 2018).
myotonic dystrophies (2 papers, 2017 to 2019). "Further analysis will be necessary to identify the precise molecular defects in insulin signalling that cause muscle insulin resistance in these two dystrophic myotonic disorders." (PMID 28915272, 2017). "Decreased insulin sensitivity is a metabolic characteristic of patients with myotonic dystrophies and in the current study we have explored the cellular mechanisms underlying this phenomenon." (PMID 28915272, 2017).
neuritis (2 papers, 2013 to 2020). A neuropathy arising from inflammation of one or more nerves. "More recent studies have reported that hyperinsulinaemia blunts insulin receptor signaling and insulin-induced survival and outgrowth of neuritis in sensory neurons." (PMID 24023699, 2013). "Moreover, the insulin pretreatment reversed the Aβ1-42-induced decrease of TUJ 1 fluorescence intensity and fragmentation of neuritis in differentiated SH-SY5Y cells (P < 0.001)." (PMID 32832007, 2020).
neuroendocrine disorder (2 papers, 2018 to 2026). A disease or disorder that affects the neuroendocrine gland, any of the organized aggregations of cells that function as secretory or excretory organs and that release hormones in response to neural stimuli. "Moreover, a poorer sleep quality is also associated with an elevation of stress levels as well as the regulation of hypothalamic-pituitary-adrenal, which can cause a neuroendocrine disorder, which in turn can cause a deregulation in the glucose-insulin metabolism." (PMID 30513771, 2018). "The type 3 diabetes hypothesis posits that AD may constitute a neuroendocrine disorder driven by disrupted insulin and insulin-like growth factor signaling." (PMID 42072320, 2026).
neurosensory deafness (2 papers, 2021 to 2024). "Clinical screening protocols for MDM are usually based on typical clinical phenotypes, including maternally inherited, the need for insulin therapy due to progressive pancreas β cell dysfunction, neurosensory deafness, and elevated serum lactate levels." (PMID 39749018, 2024).
Opportunistic infection (2 papers, 2020 to 2025). An infection that is caused by a pathogen that would generally not be able to cause an infection in a host with a normal immune system. "However, these clinical applications are limited due to insufficient tissue compatible donors, side effects of exogenous insulin administration and/or increased onset of opportunistic infections attributable to induced global immunosuppression." (PMID 32152396, 2020).
oral squamous cell carcinoma (2 papers, 2023 to 2025). "Conversely, insulin sensitizers appear to have a protective effect against cancer and may play a role in the prevention of oral squamous cell carcinoma in individuals with lichen planus." (PMID 40429290, 2025).
Osteochondrosis (2 papers, 2015 to 2018). Abnormal growth ossification centers in children. "Moreover, a functional analysis has shown that leukocytes of horses affected by osteochondrosis presented alterations of genes involved in insulin metabolism and inflammation." (PMID 29373573, 2018). "This practice, however, was shown to correlate with an increased incidence of osteochondrosis in foals, which may be related to insulin sensitivity." (PMID 25875166, 2015). "At 6 and 18 months of age, after being in pasture and/or suckling their dams, O foals were more insulin resistant than N foals without a difference in terms of osteochondrosis lesions." (PMID 29373573, 2018). "Moreover, foals that are most affected by osteochondrosis have increased post-prandial blood glucose and insulin compared to non-affected foals." (PMID 29373573, 2018).
Pancytopenia (2 papers, 2020 to 2021). An abnormal reduction in numbers of all blood cell types (red blood cells, white blood cells, and platelets). "After tocilizumab therapy, her pancytopenia fully resolved, and insulin and glucocorticoid therapies were gradually discontinued within 12 months." (PMID 33731004, 2021).
parathyroid tumors (2 papers, 2024 to 2025). "The change on plasma glucose, fasting insulin, HOMA-IR, HOMA-B%, and adiponectin did not correlate with the change in calcium or PTH as corrected upon parathyroid tumour removal." (PMID 40283231, 2025).
Peri-Implantitis (2 papers, 2019 to 2022). An inflammatory process with loss of supporting bone in the tissues surrounding functioning DENTAL IMPLANTS. "Adipogenic event is activated on peri-implantitis affected tissue: expression of peroxisome proliferator activated receptor gamma (PPARG) and insulin (INS), which regulates fatty acid storage, glucose metabolism and adipogenesis by fat cells, was detected and it is up regulated." (PMID 31242601, 2019).
pericarditis (2 papers, 2021 to 2025). An inflammatory process affecting the pericardium. "The remaining two genes were in module 1, which was enriched for inflammatory and metabolic signaling pathways, including foxO signaling, insulin signaling, and pericarditis." (PMID 41181350, 2025).
peritonitis (2 papers, 2018 to 2020). Inflammation of the peritoneum (tissue that lines the abdominal wall and covers most of the organs in the abdomen). "Indeed, the results of the present work allow us to characterize that insulin modulates important parameters that occur during peritonitis induced by S. aureus." (PMID 30705678, 2018).